TTN (titin)
Diseases named in the same sentence as TTN in open-access papers (continued):
Sharing a sentence is not in itself a finding about the gene and the disease.
type 2 diabetes (5 papers, 2014 to 2025). "In addition, in patients with type 2 diabetes, higher urinary titin concentrations are associated with the diagnosis of sarcopenia in male patients, whereas no such association was observed in female patients." (PMID 40725028, 2025). "The present study revealed that DPP‐4 inhibition reduces left ventricular stiffening in a rat model of combined type 2 diabetes, hypertension, and obesity, in part by modulating titin cleavage, isoform switching, and phosphorylation." (PMID 33295687, 2021). "This study revealed that metformin, a commonly used oral drug for the treatment of type II diabetes, ameliorates diastolic LV chamber stiffness in mice with HFpEF-like symptoms by inducing a reduction in titin-based stiffness." (PMID 30567709, 2019). "However the specific role of titin regulating diastolic (dys) function, especially in type 2 diabetes in humans, is still not clear." (PMID 24708792, 2014).
cervical cancer (4 papers, 2016 to 2025). A primary or metastatic malignant neoplasm involving the cervix. "Other studies have found significant recurrent mutations in TTN to the point that the most frequently mutated gene in cervical cancer has been identified as TTN." (PMID 41471728, 2025). "More recently, TTN mutation was reported to predict an increased tumor mutational burden, a beneficial response to immune checkpoint blockade treatment, and a long survival among pan-solid tumors, including cervical cancer." (PMID 33664766, 2021). "Therefore, an acquired mutation in the TTN gene may still result in a spontaneous case of cervical cancer." (PMID 41471728, 2025). "In addition, we found significantly recurrent mutations in TTN (33%), MUC4 (31%), and MUC16 (19%), here reported for the first time, to our knowledge, in cervical carcinomas." (PMID 33664766, 2021). "Apart from these, mutations in ODZ1, TTN and EP300 are already reported in cervical cancer." (PMID 27829003, 2016). "Therefore, the recurrent site-specific TTN and MUC4 mutations and the known role of these genes in cancer suggest the possibility that mutant TTN and MUC4 may exert oncogenic activity in cervical cancer." (PMID 33664766, 2021).
liver cancer (4 papers, 2022 to 2024). An epithelial or non-epithelial malignant neoplasm that arises from the liver.
muscle atrophy (4 papers, 2021 to 2025). The loss of muscle tissue due to inactivity or disease. "Despite these limitations, to our knowledge, this is the first study to report that urinary titin predicts long-term postoperative skeletal muscle atrophy in gastroenterological surgical patients." (PMID 40076646, 2025). "In conclusion, this study demonstrates that high levels of urinary titin on POD1 predict skeletal muscle atrophy at 6 months after surgery and may inform new approaches to improve patient prognosis." (PMID 40076646, 2025). "Thus, it is theoretically reasonable to expect levels of urinary titin to be elevated in the urine of patients with muscle atrophy." (PMID 33561946, 2021). "Unlike other promising biomarkers of muscle atrophy, urinary titin N-fragment is noninvasive and reliable." (PMID 33561946, 2021). "However, while many studies have suggested a relationship between skeletal muscle atrophy and urinary titin in the context of acute invasive procedures, none have definitively demonstrated a correlation with long-term postoperative outcomes." (PMID 40076646, 2025). "Muscle atrophy may occur because creatinine kinase, unlike titin, leaks from various tissues and is influenced by factors other than rhabdomyolysis." (PMID 40076646, 2025). "Notably, only titin levels on POD1 were significantly correlated with skeletal muscle atrophy 6 months after surgery, indicating that the acute surgical invasiveness influences long-term skeletal muscle atrophy in the postoperative period." (PMID 40076646, 2025). "Despite reduced titin protein levels in atrophic muscles 10 days after denervation, cleaved N-titin fragments were not increased in the urine of mice with denervation-induced muscle atrophy." (PMID 37582074, 2023).
Obesity (4 papers, 2019 to 2025). Accumulation of substantial excess body fat. "Obesity was associated with LV fibrosis and a transition toward β-myosin heavy chain and the N2Ba titin isoform." (PMID 37508000, 2023). "Another DPP-4 inhibitor, sitagliptin, has been shown to decrease LV cardiomyocyte Fpassive and enhance global LV performance due to elevated cGMP levels, PKG activity, and improved titin phosphorylation in a mouse model of obesity and DM." (PMID 40361188, 2025).
aortic stenosis (3 papers, 2016 to 2022). Aortic valve stenosis is a aortic valve disease caused by the incomplete opening of the aortic valve. "The expression of less Titin isoform (N2BA and N2B) was changed in left ventricular biopsies of patients with aortic stenosis." (PMID 36071494, 2022).
autoimmune encephalitis (3 papers, 2023). Inflammation of the brain secondary to an immune response triggered by the body itself. "Sera from 15 patients suspected for autoimmune encephalitis or paraneoplastic syndrome were earlier screened for binding to a commercial panel of 12 paraneoplastic antigens, including titin MIR, by dot blot (Euroimmun, Lubeck, Germany)." (PMID 36830985, 2023).
congenital heart disease (3 papers, 2017 to 2021). A heart disease that is present at birth. "An additional three individuals were found to harbour pathogenic variants in genes associated with vascular abnormalities or congenital heart defects (TTN, NKX2-6 and ARHGAP31)." (PMID 34531397, 2021). "Variations in NOTCH2, NOTCH3, TTN, TBX4, TBX10, TBX18, and TBXAS1 are associated with congenital heart disease." (PMID 29381953, 2017).
congenital myasthenic syndrome (3 papers, 2017 to 2024). Congenital myasthenic syndrome (CMS) is a group of genetic disorders of impaired neuromuscular transmission at the motor endplate characterized by fatigable muscle weakness. "Therefore, even in a case of congenital multiminicore myopathy associated with arthrogryposis and mutation absence in the RYR1, or even genes involved in congenital myasthenia or myopathy, analysis of the TTN gene and, in particular, MTT-only exons is highly recommended." (PMID 39684706, 2024).
endometrial cancer (3 papers, 2018 to 2022). Primary or metastatic malignant neoplasm involving the endometrium (mucous membrane that lines the endometrial cavity).
familial cardiomyopathy (3 papers, 2017 to 2023). An instance of cardiomyopathy that is caused by an inherited modification of the individual's genome. "RBM20 plays a role in the familial cardiomyopathy acting on titin and tropomyosin, two proteins involved in the biomechanics of the striated muscle." (PMID 35027621, 2022). "All candidate genes but one (SLC39A8) exhibit preferential expression in striated muscle tissues and mutations in TTN, BAG3, FLNC and FHOD3 are known to cause familial cardiomyopathy." (PMID 28296976, 2017). "Hence, loss-of-function mutations in human RBM20 have previously been shown to cause hereditary cardiomyopathy due to impaired Titin isoform transition and excessive production of the N2BA isoform in the RBM20-deficient hearts leading to weak Titin filaments and replacement fibrosis." (PMID 36675070, 2023).
fibrosis (3 papers, 2017 to 2026). the formation of excess fibrous connective tissue in an organ or tissue in a reparative or reactive process. "Fibrosis and titin hypophosphorylation are established contributors to diastolic stiffness in HFpEF." (PMID 41596703, 2026). "In addition, cardiac fibrosis, apoptosis and CVB3 presence were more pronounced and titin was dysregulated in CX3CR1-/- CVB3 mice compared to WT CVB3 mice." (PMID 28800592, 2017).
ischemia (3 papers, 2020 to 2025). A hypoperfusion of the BLOOD through an organ or tissue caused by a PATHOLOGIC CONSTRICTION or obstruction of its BLOOD VESSELS, or an absence of BLOOD CIRCULATION. "Therefore, we hypothesize that the difference in expression level and partially disorganized arrays of titin caused by a missense mutation may be implicated in the occurrence of ischemia-related VF." (PMID 41552678, 2025).
myocardial disease (3 papers, 2022 to 2025). "Only a small number of the TTN mutations were found to be correlated with human myocardial disease in early studies." (PMID 36304977, 2022). "In addition, pathogenic variants affecting the FNIII domain in TTN have been strongly implicated in structural myocardial diseases." (PMID 40650310, 2025). "RNA-binding motif protein 20 (RBM20), which is an important pathogenic gene of myocardial disease, is dependent on TTNcircRNAs and targets multiple key cardiac genes, such as calcium/calmodulin-dependent kinase II (CAMK2D), while also being dependent on titin (TTN) circRNAs." (PMID 35269870, 2022).
non-small cell lung carcinoma (3 papers, 2019 to 2024). A group of at least three distinct histological types of lung cancer, including non-small cell squamous cell carcinoma, adenocarcinoma, and large cell carcinoma. "GSEA performed with TCGA revealed that autoimmune thyroid disease, B-cell receptor signaling pathway, non-small-cell lung cancer, primary immunodeficiency, T-cell preceptor signaling pathway, and Toll-like receptor singling pathway were significantly enriched in samples with TTN mutation." (PMID 34746153, 2021).
ovarian serous cystadenocarcinoma (3 papers, 2023 to 2025). A malignant serous cystic epithelial neoplasm arising from the ovary. "A previous study reported several mutations within the titin gene that could serve as genetic markers in identifying ovarian serous cystadenocarcinomas." (PMID 39944242, 2025). "In this study, we investigated the relationship between social, genetic, and histopathologic factors in women with ovarian serous cystadenocarcinoma and titin (TTN) mutations, whether the TTN gene mutation may be a predictor, and its impact on mortality and survival in these patients." (PMID 37239452, 2023).
respiratory failure (3 papers, 2007 to 2025). The significant impairment of gas exchange within the lungs resulting in hypoxia, hypercarbia, or both, to the extent that organ tissue perfusion is severely compromised. "The importance of the titin–Nbr1–p62–MuRF-2 interaction is underlined by a human mutation disrupting binding of Nbr1 to titin, which causes an autosomal dominant muscle disease called heredity myopathy with early respiratory failure (HMERF)." (PMID 18047744, 2007).
restrictive cardiomyopathy (3 papers, 2016 to 2025). A type of heart disorder referring to the inability of the ventricles to fill with blood because the myocardium (heart muscle) stiffens and looses its flexibility. "Finally, the identification of a rare TTN missense variant cosegregating with the restrictive cardiomyopathy (RCM) phenotype suggests that TTN is a novel disease-causing gene in this disease." (PMID 27493940, 2016).
sarcopenia (3 papers, 2022 to 2025). Progressive decline in muscle mass due to aging which results in decreased functional capacity of muscles. "In this study, we evaluated the application of urinary titin as a diagnostic biomarker for sarcopenia in patients with unresectable digestive malignancies, focusing on sex, analyzing male and female patients separately." (PMID 40725028, 2025). "This study also demonstrated a sex-specific difference in the association between sarcopenia and urinary titin levels among patients with unresectable digestive malignancies." (PMID 40725028, 2025). "Urinary titin seems to be a useful diagnostic biomarker for sarcopenia in male patients with unresectable digestive malignancies." (PMID 40725028, 2025). "This indicates a sex difference in the association between urinary titin concentrations and sarcopenia diagnosis." (PMID 40725028, 2025). "In this study, we aimed to investigate whether urinary titin could be an effective diagnostic marker for sarcopenia in patients with unresectable gastrointestinal malignancies, with a particular focus on possible sex differences." (PMID 40725028, 2025). "The exact reason for the sex difference in the diagnostic utility of urinary titin levels for sarcopenia is currently unknown." (PMID 40725028, 2025). "In addition, sex differences have been reported in the association between sarcopenia and urinary titin levels." (PMID 40725028, 2025). "Urinary titin may serve as a useful non-invasive diagnostic biomarker for sarcopenia in patients with unresectable digestive malignancies, particularly in males." (PMID 40725028, 2025). "Importantly, multivariate logistic regression analysis revealed that urinary titin was independently associated with the diagnosis of sarcopenia in males, even after adjusting for confounding factors such as age, performance status, and nutritional status." (PMID 40725028, 2025). "The measurement in urine of titin (TTN), a muscular protein essential for structure and function of sarcomere, has been recently suggested as useful biomarker for the diagnosis of sarcopenia." (PMID 40575043, 2025). "Recently, urinary titin, a biomarker of muscle damage, has been suggested as a potential marker for sarcopenia." (PMID 40725028, 2025). "Urinary titin levels were also significantly higher among patients with sarcopenia (2.79 [95% CI: 0.54–23.8] vs. 5.78 [1.21–96.6], p = 0.008)." (PMID 40725028, 2025). "The receiver operating characteristic (ROC) analysis was performed to obtain the cutoff value of U-titin/Ucr for diagnosing sarcopenia." (PMID 40725028, 2025). "In male patients, urinary titin levels were significantly higher in the sarcopenia subgroup (5.78 vs. 2.79 pmol/mgCr, p = 0.008), and multivariate analyses identified urinary titin as an independent predictor of sarcopenia (odds ratio 13.4, p = 0.028)." (PMID 40725028, 2025). "Recently, it has been suggested that urinary titin can be an indicator of sarcopenia in preoperative patients with digestive malignancies." (PMID 40725028, 2025). "Our findings suggest that urinary titin levels can serve as a useful biomarker for diagnosing sarcopenia in patients with unresectable digestive malignancies, particularly among males." (PMID 40725028, 2025). "In male patients, urinary titin levels were significantly higher in the subgroups with sarcopenia and low handgrip strength." (PMID 40725028, 2025). "Potential biomarkers of sarcopenia include the giant sarcomeric protein titin (TTN) and its N-terminal fragment (N-TTN)." (PMID 40575043, 2025). "This study analyzed expression of TTN and N-TTN proteins in serum as possible biomarkers for sarcopenia, and evaluated whether their expression levels change following a structured rehabilitation programme." (PMID 40575043, 2025). "Among male patients, urinary titin levels were significantly higher in those with sarcopenia." (PMID 40725028, 2025).
sarcopenia (continued). "Furthermore, to evaluate the interaction effects of sex- and sarcopenia-related factors on urinary titin levels, we performed two-way analyses of variance (ANOVA)." (PMID 40725028, 2025). "This study suggests the involvement of TTN, N-TTN and miR-451a in sarcopenia; moreover, the monitoring of miR-451a concentration may be useful proxy to measure the effectiveness of rehabilitation intervention." (PMID 40575043, 2025). "Therefore, a larger concentration of titin fragments is found in the urine of people suffering from sarcopenia, making titin a useful biomarker for the condition." (PMID 35892736, 2022). "In conclusion, our results suggest that serum TTN, N-TTN and miR-451a could be valid biomarkers for sarcopenia and support the hypothesis that modulation of non-coding RNAs is a pivotal epigenetic mechanism involved in recovery after rehabilitative treatment of sarcopenic patients." (PMID 40575043, 2025). "The primary aim of our study is to evaluate the potential of serum TTN and N-TTN expression as biomarker of sarcopenia, an aspect that has not been the subject of much research so far." (PMID 40575043, 2025). "Urinary titin levels were comparatively analyzed in the sarcopenia and no-sarcopenia groups stratified by their components." (PMID 40725028, 2025).
triple-negative breast carcinoma (3 papers, 2017 to 2025). An invasive breast carcinoma which is negative for expression of estrogen receptor (ER), progesterone receptor (PR), and human epidermal growth factor receptor 2 (HER2).
arthrogryposis (2 papers, 2022 to 2024). A rare, non-progressive congenital disorder characterized by multiple joint contractures which are present at birth. "A study including genetic analysis of 315 patients with an initial phenotype of arthrogryposis shows the presence of pathogenic TTN variants in about 8% of the resolved cases, making TTN the predominant gene causing arthrogryposis." (PMID 39684706, 2024). "Our findings underscore the importance of including TTN in genetic testing panels for a wide range of neuromuscular disorders, particularly in patients presenting with early-onset myopathies and arthrogryposis." (PMID 39684706, 2024). "This work reinforces the involvement of titin in arthrogryposis and highlights the importance of the role of metatranscripts in these diseases." (PMID 39684706, 2024).
autism (2 papers, 2019 to 2021). Persistent deficits in social interaction and communication and interaction as well as a markedly restricted repertoire of activity and interest as well as repetitive patterns of behavior. "Furthermore, in our analysis, several DE miRNA targets were found to be associated with neuropsychiatric disorders, such as schizophrenia (TTN, SYNPO), depressive disorder (PPARGC1B, TIMELESS), and autism (TAF1, TRIO)." (PMID 31652596, 2019).
autoimmune thyroid disease (2 papers, 2021 to 2025). Inflammatory disease of the thyroid gland due to autoimmune responses leading to lymphocytic infiltration of the gland. "Importantly, we demonstrate that double-positive TPOAb + TgAb + status correlates with higher Titin/RyR antibody seropositivity and increased relapse risk, suggesting a potential interactions between thyroid autoimmunity and MG antibody profiles/disease progression." (PMID 41245608, 2025).
Barth syndrome (2 papers, 2025). Barth syndrome (BTHS) is an inborn error of phospholipid metabolism characterized by dilated cardiomyopathy (DCM), skeletal myopathy, neutropenia, growth delay and organic aciduria. "Several genes have been implicated in LVNC, including those responsible for encoding sarcomeric proteins (TTN and MYH7), cytoskeletal proteins (P121L), genes related to nuclear membrane components, chaperones, and the TAFAZZIN gene, causing Barth syndrome." (PMID 40004439, 2025).
Cachexia (2 papers, 2022 to 2024). Severe weight loss, wasting of muscle, loss of appetite, and general debility related to a chronic disease. "However, it seems that the decrease in the expression of titin, which we noted in the study group in comparison to the control, is connected with patient cachexia and malnutrition." (PMID 38275878, 2024).
Central core disease (2 papers, 2016 to 2024). Central core disease (CCD) is an inherited neuromuscular disorder characterised by central cores on muscle biopsy and clinical features of a congenital myopathy. "Another patient showed composed heterozygosity for both RYR1 and TTN, which supports diagnoses of two NMD, central core disease and limb-girdle dystrophy, respectively." (PMID 37989827, 2024).